RN7SL52P (RNA, 7SL, cytoplasmic 52, pseudogene)
Gene: Miscellaneous RNA gene on chromosome 21 (9,902,344 to 9,902,627, reverse strand). Ensembl gene ENSG00000264002.
Homologues: Orthologues: chimpanzee Metazoa_SRP (99% identical), macaque Metazoa_SRP (94% identical). Paralogues in human: RN7SL565P (99% identical), RN7SL722P (99% identical), RN7SL787P (99% identical), RN7SL544P (99% identical), RN7SL763P (99% identical), RN7SL205P (97% identical), RN7SL1 (81% identical), RN7SL2 (81% identical), RN7SL3 (81% identical), RN7SL322P (80% identical), RN7SL856P (80% identical), RN7SL230P (80% identical), and 702 more.